SEPTIN4 (septin 4)
Diseases named in the same sentence as SEPTIN4 in open-access papers:
SEPTIN4 is named in the same sentence as 72 diseases in open-access papers, as found by Europe PMC text mining. Sharing a sentence is not in itself a finding about the gene and the disease. The quoted sentences say what the papers report.
Infertility (6 papers, 2013 to 2025). "SEPTIN4 is vital for maintaining mitochondrial architecture during spermiogenesis, and its deregulated expression in human sperm has been linked to infertility." (PMID 40649876, 2025). "In this current research work, we elucidated and identified the presence of Septin-4 in normal healthy sperm samples and its absence or less expression in the case of other infertile groups especially in the case of motility-related issues." (PMID 34926486, 2021). "Molecular techniques characterized the presence of Septin-4 and as a novel biomarker for infertility diagnosis." (PMID 34926486, 2021). "Further research on Septin-4 with structural studies may be used to explore more on the mechanism and its role in spermatogenesis and human infertility." (PMID 34926486, 2021).
atherosclerosis (5 papers, 2020 to 2025). A disease characterized by the build-up of fatty material and calcium deposition in the arterial wall resulting in partial or complete occlusion of the arterial lumen. "It is meaningful to construct the knockout and transgenic mice of Septin4 and to explore its role in atherosclerosis in the future." (PMID 32025217, 2020). "Firstly, in order to detect Septin4 expression in atherosclerosis model in vivo, high-fat diet was used to induce atherosclerosis in Apoe-/- mice." (PMID 32025217, 2020). "Our study has the following major novel findings: 1, expression of Septin4 were markedly increased in Apoe-/- atherosclerosis mice and PDGF-BB-induced HAVSMCs." (PMID 32025217, 2020). "Here, we firstly showed that Septin4 is significantly increased during the development of atherosclerosis in Apoe-/- mice, and PDGF-BB-induced proliferation, migration and phenotypic transformation in HAVSMCs." (PMID 32025217, 2020). "3, STAT3-K685 acetylation and STAT3-Y705 phosphorylation are of critical importance in the regulation of STAT3 by Septin4 during atherosclerosis." (PMID 32025217, 2020). "We determined that the expression of Septin4 were markedly increased in Apoe-/- atherosclerosis mice and PDGF-BB-induced HAVSMCs." (PMID 32025217, 2020). "However, the role and underlying mechanism of Septin4 in atherosclerosis remains unknown." (PMID 32025217, 2020). "In vivo and in vitro results suggested that Septin4 may be involved in the regulation of atherosclerosis and HAVSMCs proliferation, migration and phenotypic transformation." (PMID 32025217, 2020). "Here, we revealed the role and mechanism of Septin4 in regulating SIRT1-STAT3 in atherosclerosis." (PMID 32025217, 2020). "We previously reported that Septin4 can aggravate the oxidative stress-induced human umbilical vein endothelial cells injury and thus may be a treatment target of some cardiovascular diseases like atherosclerosis." (PMID 34230460, 2021). "Our study firstly clarified the key role of Septin4 in inhibiting proliferation, migration and phenotype transformation of HAVSMCs by regulating SIRT1-STAT3, which provides a theoretical basis for exploring new therapeutic strategies for atherosclerosis." (PMID 32025217, 2020). "Our study firstly identified the role of Septin4 and the mechanism of Septin4-SIRT1-STAT3 complex in the proliferation, migration and phenotypic transformation of HAVSMCs, providing new ideas for the therapeutic strategies of atherosclerosis." (PMID 32025217, 2020). "However, whether Septin4 is involved in phenotypic transformation, proliferation and migration of HAVSMCs and atherosclerosis has not been reported." (PMID 32025217, 2020).
Parkinson disease (5 papers, 2013 to 2025). A progressive degenerative disorder of the central nervous system characterized by loss of dopamine producing neurons in the substantia nigra and the presence of Lewy bodies in the substantia nigra and locus coeruleus. "Septin-4, the protein encoded by the SEPT4 gene, has been identified in the alpha-synuclein-positive cytoplasmic inclusion bodies seen in Parkinson’s and related diseases." (PMID 37239136, 2023). "Interestingly, septin 4 may accumulate in tau-based deposits in both Alzheimer’s and Parkinson’s disease." (PMID 40779003, 2025).
asthenozoospermia (4 papers, 2012 to 2021). "This is believed to be an important protein Septin-4 that plays a major role in motility and its absence may be associated with asthenospermia." (PMID 34926486, 2021). "The missing protein in asthenospermia was identified as Septin-4." (PMID 34926486, 2021). "Septin 4 invalidation in the mouse resulted in male infertility due to total asthenozoospermia, and morphological defects of the flagellum, including an absence of the annulus, a bending of the flagellum and an abnormal arrangement of the mitochondria in the midpiece." (PMID 26576287, 2015).
liver fibrosis (4 papers, 2015 to 2022). "In liver fibrosis studies, some literature stand by SEPTIN4 pro‐fibrosis, but inhibiting fibrosis also was reported." (PMID 36128650, 2022). "The presence of either septin-4 (SEPT4) and septin-9 (SEPT9) was shown to attenuate liver fibrosis by decreasing TGF-beta, alpha-smooth muscle actin, and collagen I production in vivo." (PMID 31936541, 2020).
colon cancer (3 papers, 2020 to 2022). "Semiquantitative immunohistochemical analysis revealed a 1.6-fold higher level of Septin4 in peritumoral benign colon cancer cells when compared with colon cancer cells (mean score 8 vs 5, P<0.001)." (PMID 32398959, 2020). "In this study, we found that Septin4 significantly expressed lower in human colon cancer when compared to peri-tumor benign cells, and its low expression was significantly associated with worse prognostic outcomes." (PMID 32398959, 2020). "We used Septin4-overexpressing and -knockdown cell lines to demonstrate Septin4 can promote the apoptosis of colon cancer cells and ROS production." (PMID 32398959, 2020). "Septin4-overexpressing colon cancer cells displayed augmented apoptotic cell death and ROS production." (PMID 32398959, 2020). "Overexpression of Septin4 can increase the chemosensitivity of colon cancer and inhibit its progression." (PMID 32398959, 2020). "This new mechanism of Septin4 provides a theoretical basis for its potential as a new target of colon cancer treatment." (PMID 32398959, 2020). "We next explored which protein is regulated by Septin4 to promote the apoptosis of colon cancer cells induced by DOX." (PMID 32398959, 2020). "In this study, for the first time, we confirmed that Septin4 expression levels were decreased with increased colon cancer grade, and patients with high expression of Septin4 had a good prognosis." (PMID 32398959, 2020). "With colon cancer progression, we found that the expression of Septin4 decreased, which suggested that Septin4 has an important role in the inhibition of colon cancer development." (PMID 32398959, 2020). "In this study, we first confirmed that Septin4 expression levels were decreased with increased colon cancer grade, and patients with high expression of Septin4 had a good prognosis." (PMID 32398959, 2020). "We confirmed that Septin4 can promote the apoptosis of colon cancer cells by binding to BAX." (PMID 32398959, 2020). "To investigate whether Septin4 displays similar regulatory effects on the proliferation and apoptosis of colon cancer cells, we overexpressed Septin4 in HCT116 cells." (PMID 32398959, 2020). "Collectively, our data suggested that Septin4 knockdown promoted colon tumor growth in vivo." (PMID 32398959, 2020). "In conclusion, overexpression of Septin4 aggravated DOX-induced apoptosis of colon cancer cells." (PMID 32398959, 2020). "In conclusion, we revealed low Septin4 expression in colon cancer." (PMID 32398959, 2020). "The results showed that Septin4 promoted apoptosis of colon cancer cells by binding to BAX." (PMID 32398959, 2020). "As Septin4 shows a clear apoptotic effect in colon cancer cells, we speculate that mitochondrial membrane proteins may directly bind to it in addition to XIAP." (PMID 32398959, 2020). "Next, we determined the role of Septin4 in DOX-induced apoptosis of colon cancer cells." (PMID 32398959, 2020). "Furthermore, Septin4 participated in DOX-induced colon cancer cell death in vitro." (PMID 32398959, 2020). "Therefore, we speculate that in the development of colon cancer, Septin4 may also exhibit a similar effect of inhibiting tumor growth." (PMID 32398959, 2020). "We used normal colon cancer cells and Septin4-overexpressed colon cancer cells with or without 0.05 μmol/L DOX to induce apoptosis." (PMID 32398959, 2020). "In addition, Septin4 and BAX interact to regulate the apoptosis of colon cancer cells." (PMID 32398959, 2020).
colorectal cancer (3 papers, 2015 to 2021). A primary or metastatic malignant neoplasm that affects the colon or rectum. "Septin4 is a tumor suppressor protein that promotes cell programmed death in various cell types through specifically antagonizing XIAP (X linked inhibitor of apoptosis), little is known its other novel binding partner and role in colorectal cancer." (PMID 32398959, 2020).
schizophrenia (2 papers, 2021 to 2022). A major psychotic disorder characterized by abnormalities in the perception or expression of reality. "This study proposed that the SEPTIN4 gene may play an important role in the pathogenesis of schizophrenia and could be used as a biomarker for this disease." (PMID 35328011, 2022).
chronic obstructive pulmonary disease (1 paper, 2025). A chronic and progressive lung disorder characterized by the loss of elasticity of the bronchial tree and the air sacs, destruction of the air sacs wall, thickening of the bronchial wall, and mucous accumulation in the bronchial tree. "Expression of SEPTIN4, a gene that may be involved in apoptosis, was associated with annual mean O3 and has been reported to be a part of a biomarker gene set to discriminate between chronic obstructive pulmonary disease and interstitial lung disease." (PMID 40510537, 2025).
fibrosis (1 paper, 2021). the formation of excess fibrous connective tissue in an organ or tissue in a reparative or reactive process. "In addition, Septin4 can also inhibit the growth of hepatic stellate cells and negatively regulates the hepatic fibrosis through TLR4/TGF-β or PI3K/Akt pathway." (PMID 34230460, 2021).
male infertility (1 paper, 2021). The inability of the male to effect fertilization of an ovum after a specified period of unprotected intercourse. "In-silico finding acts as a critical point that can initiate various structure-function studies on human Septin-4 toward male infertility mechanism and pharmacology aspects." (PMID 34926486, 2021). "Till now many researchers worked with labeling techniques and identified the importance of Septin-4 in the case of male infertility." (PMID 34926486, 2021). "The role of Septin-4 in male infertility is enormous and more molecular work is in need for the prediction of the pathway mechanism behind male infertility." (PMID 34926486, 2021). "Moreover, the advance of in-silico studies deciphered the structural annotation of human Septin-4 that can be used to understand the role of septin in male infertility." (PMID 34926486, 2021). "Hence, our findings concluded that Septin-4 was a novel biomarker for male infertility and can be used for diagnosis and pharmacology purposes." (PMID 34926486, 2021).
prostate carcinoma (1 paper, 2021). A carcinoma that arises from epithelial cells of the prostate gland. "Contrary to the finding in the current study that Septin4 can promote apoptosis by reducing HIF-1α levels in cardiomyocytes, it has been reported that other proteins in the Septin family like Septin9, can promote tumorigenesis by stabilizing HIF-1α levels in human prostate cancer cells." (PMID 34230460, 2021).
pulmonary fibrosis (1 paper, 2022). Chronic progressive interstitial lung disorder characterized by the replacement of the lung tissue by connective tissue, leading to progressive dyspnea, respiratory failure, or right heart failure. "That may establish a pro‐fibrotic role for the Orai3 and a mechanism via SEPTIN4 regulating Orai channel remodelling in pulmonary fibrosis." (PMID 36128650, 2022).
tumor (32 papers, 2005 to 2025). "The Septin4 deficient HCT116 cells demonstrated larger tumor size than the normal control HCT116 cells." (PMID 32398959, 2020). "Moreover, unlike traditional tumor suppressors or oncogenes, whose loss- or gain-of-function mutations can lead to the occurrence of cancer 17, Septin4 can affect tumor occurrence through expression changes, which makes it a more universal cancer suppressor." (PMID 32398959, 2020). "Then we performed tumor formation in vivo, which revealed that Septin4 knockdown accelerated subcutaneous tumor growth in nude mice." (PMID 32398959, 2020). "To clarify the mechanism of Septin4 in promoting the apoptosis of tumor cells, we found that Septin4 can interact with BAX and enhance this interaction following stimulation with DOX." (PMID 32398959, 2020). "Increased levels of septin 2, 8, 9, 11 and decreased levels of septin 4 and 10 have been consistently reported in various tumor types and are assumed to act as oncogenes and tumor suppressor genes, respectively." (PMID 29699512, 2018). "Furthermore, compared with normal control cells, Septin4-knockdown HCT116 cells also had a greater tumor weight." (PMID 32398959, 2020). "Moreover, the difference in Septin4 gene expression is related to tumor grade, stage, and prognosis." (PMID 32398959, 2020). "With the recent in-depth study of the cell biological function of Septin4, accumulating evidence has suggested that Septin4 is involved in the regulation of tumor cell death, proliferation, angiogenesis, and invasion, which is a marker of these molecular mechanisms." (PMID 32398959, 2020). "Together, these findings indicated that Septin4 could inhibit the proliferation of tumor cells." (PMID 32398959, 2020).
cancer (16 papers, 2004 to 2025). A tumor composed of atypical neoplastic, often pleomorphic cells that invade other tissues. "Aberrant expression of septins is involved in tumorigenesis, e.g., overexpression of septin-2,-8,-9,-11 and downregulation of septin-4 and septin-10 have been identified in a wide variety of cancer types." (PMID 27525972, 2016). "This also suggested that Septin4 may act as a potential oncogene or tumor suppressor gene in the development of some cancer types." (PMID 32398959, 2020). "There are plenty of regulatory proteins, including CRACR2A, SEPTIN4, STIMATE, GOLLI, SARAF, ORMDL3 and so on, that contribute to alter SOCE activity in cancer, immune diseases and inflammation disorders." (PMID 36128650, 2022).
cardiovascular diseases (2 papers, 2020 to 2021). "It will also be significant to explore the role and mechanism of Septin4 in other cardiovascular diseases." (PMID 32025217, 2020).
neurodegenerative disease (2 papers, 2021 to 2025). A disorder of the central nervous system characterized by gradual and progressive loss of neural tissue and neurologic function. "Septin 4 (SEPT4), a GTPase previously found in neurofibrillary tangles of AD and in LB was also found to be a substrate of DYRK1A in neocortical neurons, expanding the mechanisms by which DYRK1A is implicated in neurodegenerative diseases." (PMID 34828439, 2021).
SEPTIN4 also shares sentences with these, for which no sentence is quoted: melanoma (29 papers); infection (11); acute lymphoblastic leukemia (4); Hypertension (3); breast carcinoma (2); Down syndrome (2); glioma (2); influenza (2); lung carcinoma (2); ovarian carcinoma (2); pancreatic cancer (2); Alzheimer disease (1); Arrhythmia (1); autoimmune disease (1); bacterial disease (1); bipolar disorder (1); cardiac hypertrophy (1); cardiomyopathy (1); cervical cancer (1); cholera (1); colitis (1); dementia (1); dementia with Lewy bodies (1); depression (1); epididymitis (1); fragile X syndrome (1); gastroenteritis (1); head and neck squamous cell carcinoma (1); heart failure (1); hepatocellular carcinoma (1).
A further 25 diseases each share a sentence with SEPTIN4 in 1 paper.